FAM230F (family with sequence similarity 230 member F)
Synonyms: formerly LINC01663
Gene: Long non-coding RNA gene on chromosome 22 (18,873,543 to 18,896,777, reverse strand). Ensembl gene ENSG00000276095.
Diseases named in the same sentence as FAM230F in open-access papers:
FAM230F is named in the same sentence as 3 diseases in open-access papers, as found by Europe PMC text mining. Sharing a sentence is not in itself a finding about the gene and the disease. The quoted sentences say what the papers report.
autism spectrum disorder (1 paper, 2021). A spectrum of developmental disorders that includes autism, and Asperger syndrome. "A recent case control study reported microdeletions encompassing the PRODH and DGCR6 genes to be a strong risk factor for hyperprolinemia type 1 but not for autism spectrum disorder suggesting more emphasis on the other lesser known FAM230F and DGCR5 genes." (PMID 34938854, 2021).
schizophrenia (1 paper, 2021). A major psychotic disorder characterized by abnormalities in the perception or expression of reality. "Refseq genes in this region include FAM230F, DGCR6, PRODH, DGCR5, with pathogenic PRODH variants associated with autosomal recessive hyperprolinemia type I or autosomal susceptibility to schizophrenia." (PMID 34938854, 2021).
FAM230F also shares sentences with these, for which no sentence is quoted: hyperprolinemia type 1 (1 paper).